RN7SL384P (RNA, 7SL, cytoplasmic 384, pseudogene)
Gene: Miscellaneous RNA gene on chromosome 10 (114,423,770 to 114,424,067, reverse strand). Ensembl gene ENSG00000242912.
Homologues: Orthologues: chimpanzee Metazoa_SRP (99% identical), macaque Metazoa_SRP (93% identical). Paralogues in human: RN7SL1 (81% identical), RN7SL2 (81% identical), RN7SL543P (80% identical), RN7SL709P (80% identical), RN7SL3 (79% identical), RN7SL122P (79% identical), RN7SL597P (79% identical), RN7SL791P (79% identical), RN7SL63P (79% identical), RN7SL444P (78% identical), RN7SL664P (78% identical), RN7SL88P (78% identical), and 705 more.